PRDX2 (peroxiredoxin 2)
Diseases named in the same sentence as PRDX2 in open-access papers (continued):
Sharing a sentence is not in itself a finding about the gene and the disease.
tumor (continued). "IHC results demonstrated that the expression of PRDX2 was significantly increased in HCC tumor tissues compared to that in para-tumor tissues." (PMID 38188679, 2023). "On the contrary, PRDX2 acts as a tumor suppressor molecule depending on the tumor type and tumor stage." (PMID 37501157, 2023). "Then we explored the relationship between PRDXs and tumor stage and found that only PRDX2, PRDX3, and PRDX4 were significantly correlated with COAD stage." (PMID 36969053, 2023). "Formalin-fixed, paraffin-embedded (FFPE) tissue from 119 cases of urothelial cancer and 5 cases with normal mucosa was used to evaluate the expression and localization of the protein (PRDX1 and PRDX2) in the tumor by immunohistochemistry." (PMID 35812179, 2022). "For example, PRDX2 can participate in the regulation of tumor development and oxidative stress in treatment through the PI3/AKT-resistant pathway." (PMID 36141135, 2022). "We reported that circDIDO1 exerted a tumor suppressor role by encoding a novel 529 aa protein (DIDO1-529aa) to inhibit PARP1 activity and binding to PRDX2 protein to promote its degradation." (PMID 34384442, 2021). "Western blot results confirmed that circDIDO1 overexpression inactivated these pathways in GC cells and tumor tissues, which shares a similar change pattern to those observed in GC cells with PRDX2 knockdown." (PMID 34384442, 2021). "In the present study, we assessed PRDX2 expression in these patients by IHC, with 10 tumor tissues with liver metastasis collected from these individuals." (PMID 33819194, 2021). "In our previous study, we determined that PRDX2 is differentially expressed in CRC tissue compared to adjacent normal tissue; increased expression is associated with poor tumor differentiation and advanced “tumor, node, metastasis” (TNM) stages." (PMID 32692719, 2020). "We also revealed a regulatory loop by which PRDX2 inhibits tumor metastasis and chemotherapeutic resistance." (PMID 32692719, 2020). "Comparison of the transcript-per-million values in normal and primary tumor tissues verified PRDX2 overexpression in BRCA, CHOL, LIHC, LUAD, PRAD and UCEC." (PMID 32692719, 2020). "Unsurprisingly, we found that PRDX2 acts as a tumor promoter involved in the induction of cell proliferation, cell-cycle progression and inhibition of apoptosis in oral cell lines." (PMID 33332365, 2020). "Collectively, the Akt/mTOR signaling pathway is involved in the tumor-promoting effect of PRDX2 in NSCLC cells." (PMID 32337219, 2020). "In order to test the influences of PRDX2 expression in the more complex in vivo environment, we examined the NSCLC cell tumorigenicity by xenograft model and found that knockdown PRDX2 weakened the tumor formation in vivo." (PMID 32908916, 2020). "PRDX2 has also been shown to play a tumor-promoting role in CRC and to have prognostic value for CRC patients." (PMID 32692719, 2020). "PRDX2 has been shown to play a tumor-promoting role in CRC and to have prognostic value for CRC patients." (PMID 32692719, 2020). "Early studies showed that Prdx2 inhibited the myeloid cell proliferation by reducing ROS levels and acted as an epigenetically silenced tumor suppressor in AML." (PMID 33425206, 2020). "The results presented that a marked decrease in the numbers of Ki-67-positive (Ki-67+) cells and PCNA-positive (PCNA+) cells was observed in PRDX2-knockdown tumor tissues, indicating PRDX2 knockdown suppressed cell proliferation in vivo." (PMID 32908916, 2020). "Peroxiredoxin 2 is a redox regulatory protein that plays an important role in maintaining ROS homeostasis in the tumor microenvironment by coupling with the thioredoxin/thioredoxin reductase system." (PMID 32846884, 2020). "For early stage (stage I-II) patients, univariate analysis showed that PRDX2 expression, tumor differentiation grade and patient age were significantly related with DFS and DSS." (PMID 28125800, 2017).
tumor (continued). "Peroxiredoxin 2 (PRDX2) is an antioxidant and molecular chaperone that can be secreted from tumor cells." (PMID 28765537, 2017). "The present study reveals that disruption of the c-Myc/miR-200b-3p/PRDX2 regulatory loop enhances tumor metastasis and chemotherapeutic resistance of CRC cells, and contributes to unfavorable outcome of CRC patients." (PMID 29258530, 2017). "In our tumor tissues, we identified the sporadic expression of 9 detox proteins (encoded by seven genes), namely: SODC, CATA, PRDX2, PRDX6, GSTP1, ALDR and AK1BA." (PMID 28686225, 2017). "We found that PRDX1 and PRDX2 are upregulated in tumor B cells as compared with normal counterparts." (PMID 26636537, 2016). "Prdx2, a typical 2-Cys peroxiredoxin, has higher expression levels in tumorous colon tissues compared with the corresponding normal non-tumor tissues, and Prdx2 knockdown inhibits cell growth and stimulates apoptosis." (PMID 27894099, 2016). "To evaluate the in vivo effects of Prdx2 knockdown, we used a subcutaneous xenotransplant tumor model by injecting the CD133+ cells sorted from HCT116-shPrdx2 or HCT116-shCont into female BALB/c-nu mice." (PMID 27894099, 2016). "To extend these observations, we analyzed the expression of PRDX1 and PRDX2 in a panel of B cell-derived tumor cell lines." (PMID 26636537, 2016). "Unexpectedly, 9 genes showed the inverse association, including the tumor suppressor genes: RUNX1, CBX7, PRDX2 and PRDX3." (PMID 23077491, 2012). "Studies have also shown that overexpression of peroxiredoxin 2 protein inhibits cisplatin-induced apoptosis, thereby contributing to chemoresistance in tumour cells." (PMID 19367286, 2009). "Moreover, while the rescue with WT PRDX2 restored tumor spheroid and colony formation, the peroxidase-inactive C51S mutant showed the same profile as PRDX2-KO cells, indicating that the antioxidant function of PRDX2 is involved in tumor initiation." (PMID 40932790, 2025). "We hypothesize that targeting PRDX2 may have an impact on tumor initiation through its antioxidant function." (PMID 40932790, 2025). "Finally, PRDX2 KO reduced the expression of the CD44 stem cell marker in tumors, supporting the role of PRDX2 in stemness and tumor initiation." (PMID 40932790, 2025). "PRDX2 silencing significantly inhibited tumor growth in mice." (PMID 38188679, 2023). "Western blot results also confirmed the increased protein level of PRDX2 in HCC tumor tissues." (PMID 38188679, 2023). "This low reduction capacity of oxidized Prdx2 is a specific feature of erythrocytes and some other cells (e.g., hepatocytes), while the majority of tumor cell lines maintain the capacity for the reduction of oxidized Prdx2 in slight excess over the maximal steady-state Prdx2 oxidation." (PMID 37237878, 2023). "Peroxiredoxin-2 is an antioxidant enzyme that balances reactive oxygen species and cytokine-induced peroxide levels via electron transfer mediation and is considered essential for tumour cell maintenance and survival." (PMID 34832109, 2021). "In addition, in the invasion front of tumor tissues, PRDX2 overexpression was also predominantly observed." (PMID 33819194, 2021). "To investigate whether PRDX2 plays an oncogenic role in vivo, we performed a xenograft tumor growth experiment by subcutaneously injecting shPRDX2-HCT116 and NC-HCT116 cells into the dorsal flank." (PMID 34117220, 2021). "Inversely, PRDX2 functions as a tumor suppresser in acute myeloid leukemia." (PMID 33332365, 2020). "Silencing PRDX2 restrained tumor growth and repressed lung metastasis by EMT in vivo." (PMID 32908916, 2020). "Indeed, overexpression of Prdx2 partially reversed the inhibitory effect of Celastrol on tumor growth." (PMID 32929349, 2020). "We hypothesized that PRDX2 act as a tumor promoter via neutralizing hydrogen peroxide contributing to the protection of cells from oxidative damage and the regulation of peroxide-mediated signal transduction in oral cell lines." (PMID 33332365, 2020).
tumor (continued). "In summary, PRDX2 acts as a tumor promoter in oral cell lines and its dysregulation could be induced by arecoline and HPV16 E6/E7." (PMID 33332365, 2020). "For PRDX2, its moderate expression in glandular cells was shown in all the three colon tissues while in tumor cells, its strong expression was shown in six of the seven COAD tissues (Likelihood Ratio = 7.719, p=0.005), consistent with it up-regulation in COAD in mRNA level in above analyses." (PMID 32231717, 2020). "Low expression of Prdx‐2 in tumor cells makes them more sensitive to oxidative damage." (PMID 32232956, 2020). "PRDX2 can show a tumor‐promoting effect or tumor‐suppressive function based on tumor type." (PMID 31417643, 2019). "The tumor promoting role of PRDX2 in CRC was firstly reported by our research group." (PMID 28125800, 2017). "In addition, we found that PRDX2 depletion in mice treated with 5-FU resulted in, inhibition of tumor growth, compared with mice treated with 5-FU alone." (PMID 28432271, 2017). "The lower expression of PRDX-2 suggests that it may be as a tumor suppressor, of course, its mechanism remains to be further research." (PMID 27966448, 2017). "In addition to the Western blotting, six tumor samples were further detected for PRDX2 expression by immunohistochemical analysis." (PMID 28125800, 2017). "Moreover, we elucidated the contribution of the c-Myc/miR-200b/PRDX2 regulatory loop to the tumor EMT, metastasis, chemotherapeutic resistance and prognostic significance in CRC patients." (PMID 29258530, 2017). "In conclusion, our findings suggest PRDX2 up-regulation correlates with tumor progression and could serve as a useful marker for the prognosis of CRC." (PMID 28125800, 2017). "In addition, PRDX2 depletion in vivo in combination with 5-FU treatment, markedly inhibited tumor growth compared with treatment with 5-FU alone." (PMID 28432271, 2017). "Also the antioxidant enzyme peroxiredoxin 2 (PRXD2) (antiapoptosis) was highly upregulated in the NE tumour cell group." (PMID 18827820, 2008). "Therefore, specific EV packaging of peroxiredoxin-2 in the scenario (responder) may scavenge tumour supplies and lead to reduced cell survival, a phenomenon that is consistent with response to therapy." (PMID 34832109, 2021). "This may be a potential mechanism of PRDX2-dependent tumor proliferation or drug resistance." (PMID 34117220, 2021). "PRDX2, PKD2 (polycystin-2), and AQP1 were overexpressed in tumor tissues, whereas SOD3 and KLF2 were downregulated." (PMID 41140697, 2025). "SOX11 knockout (SOX11KO) significantly reduced PRDX2 expression, and SOX11KO and PRDX2 knockdown (PRDX2KD) had increased ROS levels and ROS-mediated tumor cell death upon treatment with drugs, compared to control MCL cell lines." (PMID 38570586, 2024). "In the current study, we set out to examine the levels of both PRDX1 and PRDX2 in GBM and non-tumor (NT) brain tissues." (PMID 37566013, 2023). "To investigate the potential oncogenic role of PRDX2 in HCC, we analyzed TCGA data and examined the expression change of PRDX2 in the tissues of HCC patients, including tumor tissues and adjacent non-tumor tissues." (PMID 38188679, 2023). "The peroxiredoxin-2 (PRDX2) enzyme inhibitor, N-carbamoyl alanine (NCA), was carried by nanoparticles to deliver drugs to tumor tissues more efficiently." (PMID 39524544, 2023). "The protein expression of PRDX2 was remarkably higher and frequently upregulated in CD133(+)/CD44(+) tumor tissues compared to CD133 (-)/CD44(-) tumor tissues." (PMID 33819194, 2021). "PRDX2 expression was remarkably higher and more frequently upregulated in CD133(+)/CD44(+) tumor tissues compared to CD133(-)/CD44(-) tumor tissues." (PMID 33819194, 2021).
tumor (continued). "On the contrary, PRDX2 and PRDX3 showed higher expression levels in C4 subtypes, indicating that they are involved in tumor suppression." (PMID 34246267, 2021). "Our results demonstrated that PRDX2 knockdown inhibits the self-renewal capacity of CD133+CD44+ CCSCs in vitro and the tumor incidence and growth of these cells in vivo." (PMID 33819194, 2021). "The mRNA expression of PRDX2, CD133 and CD44 in tumor tissues was significantly upregulated compared to that observed in ANTs tissues." (PMID 33819194, 2021). "It has been shown that PRDX2 downregulated the expression of Dynamin 3 (DNM3), which is one member of the guanylate triphosphatases (GTPases) family and exerts as an important tumor suppressor." (PMID 32908916, 2020). "For the enhancer in chromosome 19, the target genes are TRMT1, TNPO2, NFIX, DNASE2, PRDX2, NANOS3, and LYL1, which was detected in 22 unique tumor samples." (PMID 29207666, 2017). "High PRDX2 expression was significantly related with local invasion (p = 0.046), TNM stage of CRC (p = 0.020), tumor differentiation (p = 0.001), and lymph node metastasis (p = 0.008)." (PMID 28125800, 2017). "Our findings reveal that the c-Myc/miR-200b/PRDX2 loop regulates CRC progression and its disruption enhances tumor metastasis and chemotherapeutic resistance in CRC." (PMID 29258530, 2017). "Univariate analysis results showed DFS and DSS were related with the expression of PRDX2, TNM stage of CRC, tumor differentiation grade and patient age." (PMID 28125800, 2017). "In line with the inhibitory effect of isoform II-knockdown on tumor growth, CAL 27 cells stably transfected with anti-PRDX2 shRNAs showed notably reduced tumor growth and weight than those transfected with non-specific control shRNA in nude mice." (PMID 40498062, 2025). "Analysis of PRDX2 expression using publicly available data (GEO and The Cancer Genome Atlas) revealed that PRDX2 expression was increased in tumor liver tissues compared with adjacent nontumoral tissues." (PMID 40932790, 2025). "In addition, CLT in HCR NPs induced ROS-mediated apoptosis by inhibiting PRDX2, and IR820 increased the temperature at the tumor site with 808 nm laser irradiation to further enhance the therapeutic effect both in vitro and in vivo." (PMID 36670444, 2023). "PRDX1 and PRDX2 were both found to be expressed in tumor cells and these proteins were absent in normal mucosa evaluated as control." (PMID 35812179, 2022). "In addition, the expression of PRDX2 and PRDX5 in the GPx2 KD tumor was increased by 1.3-fold (logFC = 0.4) and catalase by 1.2-fold (logFC = 0.27), whereas the expression of SOD2 was unchanged." (PMID 35193955, 2022). "Furthermore, PRDX2 depletion markedly suppressed CD133+CD44+ CCSC stemness maintenance, tumor initiation, migration and invasion and liver metastasis." (PMID 33819194, 2021). "Interfering with the interaction between PRDX2 and RPL4 may reverse the chemoresistance of tumor cells." (PMID 34117220, 2021). "Furthermore, we found that combined inhibition of PI4KIIα and EGFR suppressed both PI3K/AKT and MAPK/ERK pathways, and resulted in downregulation of multiple oncogenes like PRDX2, FASN, MTA2, ultimately leading to suppression of tumor growth." (PMID 24801752, 2014). "PRDX2 KO reduced tumor growth, with 3 out of 10 PRDX2-KO mice not showing any tumor formation." (PMID 40932790, 2025). "In line with the crucial function of peroxiredoxins neutralizing ROS generated by oxidative stress in tumor cells, we observed a significant positive correlation between ROS and PRDX2 mRNA levels, but not with other PRDXs (data not shown), in these MCL primary tumors." (PMID 38570586, 2024).
tumor (continued). "However, in SOX11− MCL cells, the low levels of PRDX2 are not able to manage oxidative stress generated during chemotherapy, and eventually tumor cells die upon treatments due to the increased lethal levels of ROS in SOX11− MCLs cells." (PMID 38570586, 2024). "Moreover, the effects of PRDX2 regulation on intracellular signaling of PRDX6 have been correlated with different aspects of tumor behavior such as invasive, apoptosis, as well as, resistance to chemotherapeutic agents and tumor recurrence." (PMID 37501157, 2023). "In addition, a recent study demonstrated that a novel circular RNA DIDO1 could specifically bind to PRDX2 and promote its ubiquitination and degradation in a RBX1-dependent way, which inhibited its downstream signaling pathways to suppress tumor progression." (PMID 35813474, 2022). "We further showed that PRDX2 is functionally required for CD133+CD44+ CCSC stemness maintenance, tumor initiation, migration and invasion, and liver metastasis, and the expression of various EMT markers and Wnt/β-catenin signaling proteins was altered after PRDX2 inhibition." (PMID 33819194, 2021). "In addition, the IHC results showed that PRDX2 expression was enhanced in the orthotopic tumor tissues from metastatic mice compared to tumor samples from nonmetastatic mice." (PMID 33819194, 2021). "The levels of Prdx2 proteins were not altered in tumor tissues." (PMID 32929349, 2020). "Western blotting from the tumor tissue corroborated these observations, showing diminished GPX4 levels without alterations in PRDX1 and PRDX2 expressions." (PMID 40645965, 2025). "There was no significant change in the protein expression of PRDX1, PRDX2 and CD20 (a DLBCL tumor cell marker) in either the control group or the ART group." (PMID 40645965, 2025). "All PRDXs were highly expressed in BLCA tumor tissues compared with normal tissues, though there is no significant different in expression levels of PRDX2, PRDX3 between tumor and normal tissues." (PMID 34246267, 2021). "The up-regulation of PRDX2, down-regulation of PRDX6, and the nuclear absence of PRDX1 in COAD tumor cells were indicated." (PMID 32231717, 2020).
infection (7 papers, 2011 to 2025). The state of being infected such as from the introduction of a foreign agent such as serum, vaccine, antigenic substance or organism. "Up-regulated levels were found for MRC1(Macrophage mannose receptor C type-1) and PRDX2 (Peroxiredoxin 2) following experimental infection with APP." (PMID 32632500, 2020). "The level of BmTPx-Q expression reached a peak, whereas B. microti parasitemia decreased to low levels at 8 days post-infection, similar results were also observed for B. microti other antioxidant enzymes, such as peroxiredoxin 2, thioredoxin 2, and thioredoxin 3 in previous studies." (PMID 32133382, 2020). "This appears to be highly specific, since amounts of PRDX1-4 or PRDX2 did not change during infection (lane 5–8)." (PMID 23210548, 2012). "On the individual gene level PRDX2, an antioxidant enzyme was enriched in the acute stage of secondary DENV infection, while at defervesence, CCR2 was among the transcripts seen upregulated in secondary infection." (PMID 21810247, 2011).
neurological disorders (5 papers, 2012 to 2024). "PRDX2 has been implicated in neurological disease due to aberrant management of ROS54." (PMID 38086949, 2023). "Among them, LCN2, TIMP1, S100A8/9, and PRDX2 related to host response and/or inflammation in neurological disorders, could be used as potential biomarkers of brain pathology." (PMID 24695528, 2014). "S-nitrosylation of Parkin, protein disulfide isomerase (PDI), peroxiredoxin 2 (Prx2), X-linked inhibitor of apoptosis (XIAP), and Drp1 has been implicated in stress-induced neuronal death and has been also observed in brains from patients with neurological disorders." (PMID 22927857, 2012). "Reports have shown that Prdx2 can reduce reactive oxygen species (ROS) production by catalyzing H2O2 to water, which maintains intracellular redox homeostasis and attenuates various neurological disorders." (PMID 36832865, 2023).